USP21 (ubiquitin specific peptidase 21)
Description:
Deubiquitinates histone H2A, a specific tag for epigenetic transcriptional repression, thereby acting as a coactivator (By similarity). Deubiquitination of histone H2A releaves the repression of di- and trimethylation of histone H3 at 'Lys-4', resulting in regulation of transcriptional initiation (By similarity). Regulates gene expression via histone H2A deubiquitination (By similarity). Deubiquitinates BAZ2A/TIP5 leading to its stabilization. Also capable of removing NEDD8 from NEDD8 conjugates but has no effect on Sentrin-1 conjugates. Also acts as a negative regulator of the ribosome quality control (RQC) by mediating deubiquitination of 40S ribosomal proteins RPS10/eS10 and RPS20/uS10, thereby antagonizing ZNF598-mediated 40S ubiquitination.
Synonyms: USP23; USP16
Tractability: Small molecule: a structure with a bound ligand is known; it has a binding pocket of medium quality. Antibody: its Gene Ontology location is reachable by antibodies, with high confidence. PROTAC: ubiquitination databases record sites on it.
Target class: Enzyme
Chemical probes: BAY-805 (high quality)
Gene: Protein-coding gene on chromosome 1 (161,159,450 to 161,165,723, forward strand). Ensembl gene ENSG00000143258.
Subcellular location: Cytoplasm; Nucleus
Subcellular location (Human Protein Atlas): Cytosol; Nucleoplasm; Plasma membrane
Pathways (Reactome):
Signal Transduction: Regulation of TNFR1 signaling; TNFR1-induced NF-kappa-B signaling pathway; TNFR1-induced proapoptotic signaling
Metabolism of proteins: Ub-specific processing proteases
Gene Ontology:
Molecular function: cysteine-type deubiquitinase activity; cysteine-type peptidase activity; deNEDDylase activity; protein binding; transcription coactivator activity
Biological process: protein deubiquitination; transcription initiation-coupled chromatin remodeling; positive regulation of DNA-templated transcription
Cellular component: cytoplasm; cytosol; nucleoplasm; nucleus
Genetic constraint (gnomAD): Loss-of-function variants: 37 observed, 72.5 expected, observed/expected ratio (o/e) 0.51, 90% interval 0.39 to 0.67. The upper end of that interval is the gene's LOEUF score, 0.67, which puts it in group 2 of 6, group 1 being the genes least tolerant of losing a copy. Missense variants: 582 observed, 775.54 expected, observed/expected ratio (o/e) 0.75, 90% interval 0.7 to 0.8. Synonymous variants: 263 observed, 299.46 expected, observed/expected ratio (o/e) 0.88, 90% interval 0.79 to 0.97.
Homologues: Orthologues: chimpanzee USP21 (99% identical), macaque USP21 (99% identical), pig USP21 (98% identical), rabbit USP21 (98% identical), dog USP21 (97% identical), mouse Usp21 (96% identical), rat Usp21 (96% identical), guinea pig USP21 (95% identical), tropical clawed frog usp21 (59% identical), zebrafish usp21 (35% identical), Drosophila melanogaster Usp2 (33% identical). Paralogues in human: USP2 (39% identical), USP19 (29% identical), USP4 (26% identical), USP15 (25% identical), USP11 (25% identical), USP8 (25% identical), USP31 (24% identical), USP43 (24% identical), USP9X (24% identical), USP32 (24% identical), USP24 (23% identical), USP9Y (23% identical), and 59 more.
Diseases named in the same sentence as USP21 in open-access papers:
USP21 is named in the same sentence as 63 diseases in open-access papers, as found by Europe PMC text mining. Sharing a sentence is not in itself a finding about the gene and the disease. The quoted sentences say what the papers report.
bladder cancer (13 papers, 2017 to 2025). "USP21 is upregulated in bladder cancer (BC) and ectopic expression of USP21 is closely associated with tumor size and metastasis." (PMID 30150556, 2018). "USP21, in turn, was stabilised by circCD2AP, a circular RNA that was found to be increased in bladder cancer." (PMID 39777582, 2025). "In bladder cancer cells, increased expression of USP21 promoted cell proliferation, stimulated cell migration and invasion, enhanced tumor metastasis." (PMID 37215134, 2023). "In bladder cancer, USP21 is highly expressed and patients with high expression levels have poor survival, and USP21 can accelerate the proliferation and metastasis of bladder cancer cells via inhibiting EZH2 ubiquitination." (PMID 33791299, 2021). "USP21 is overexpressed in bladder cancer and its overexpression promotes deubiquitination and stabilization of EZH250." (PMID 30918246, 2019). "Previous studies have established that USP21 is an oncogene in some malignancies, including kidney and bladder cancer as well as HCC13,22–24." (PMID 29706623, 2018). "USP21 facilitates cell proliferation, epithelial-mesenchymal transition and metastasis in bladder carcinoma cell lines." (PMID 30150556, 2018). "Wang and colleagues reported that USP21 stabilises FOXQ1 in bladder cancer cells." (PMID 39777582, 2025). "Another study showed that USP21 expression was elevated in bladder cancer." (PMID 37215134, 2023). "Notably, 20-hydroxyecdysone (20-HE) can directly inhibit NF-κB/p65 signaling at the transcriptional level while also serving as an inhibitor of USP21, leading to p65 protein degradation and the blockade of its activation, ultimately preventing the progression of bladder cancer." (PMID 40771930, 2025). "USP21 could be a potential target for bladder cancer therapy." (PMID 37215134, 2023). "Some studies have also found that USP14 and USP21 could function as oncogenes in bladder cancer." (PMID 34769137, 2021). "Previous studies have demonstrated that USP21 and USP14 were upregulated in bladder carcinoma and played an important role in tumor cell proliferation and metastasis." (PMID 34769137, 2021). "Another study showed that USP21 expression is upregulated in bladder tumors and suggested that USP21 could promote cancer growth and metastasis by inhibiting the ubiquitylation of EZH2 in bladder cancer cell lines." (PMID 28969054, 2017).
hepatocellular carcinoma (12 papers, 2017 to 2026). A malignant tumor that arises from hepatocytes. "The high expression of USP21 in hepatocellular carcinoma is associated with a lower survival rate among hepatocellular carcinoma patients." (PMID 39048965, 2024). "USP21 stabilizes MEK2 by removing K48-linked PUCs, thereby activating the ERK signaling cascade and promoting hepatocellular carcinoma (HCC) progression." (PMID 41436460, 2025). "In hepatocellular carcinoma cells, USP21 directly interacts with and stabilizes MEK2 by decreasing its K48-linked polyubiquitination, thus activating the MAPK/ERK branch, where MAPKKK is Raf, MAPKK is MEK, and MAPK is ERK." (PMID 35846989, 2022). "Recent studies showed that USP21 is overexpressed in several tumors such as hepatocellular carcinoma." (PMID 31947604, 2020). "Consistent with our previous findings, USP21 overexpression in hepatoma cell lines resulted in increased MEK2 expression." (PMID 29706623, 2018). "Consistent with our previous findings, USP21 knockdown in hepatoma cell lines resulted in reduced BRCA2 expression and a concomitant increase in DNA damage, as measured by H2AX phosphorylation." (PMID 28743957, 2017). "The most pronounced increase in USP21 mRNA was observed in liver cancer, including cholangiocarcinoma and hepatocellular carcinoma (HCC)." (PMID 28743957, 2017). "Consequently, USP21 depletion reduced the efficiency of HR, leading to increased DNA damage load and concomitant impairment of hepatocellular carcinoma (HCC) cell survival." (PMID 35846989, 2022). "For instance, USP10 and USP21 could promote hepatocellular carcinoma and non-small-cell lung cancer proliferation, respectively." (PMID 34261480, 2021). "Moreover, we show that USP21 is overexpressed in hepatocellular carcinoma, where it promotes BRCA2 stability and inversely correlates with patient survival." (PMID 28743957, 2017). "For instance, USP21 induced the activation of the ERK signaling pathway by deubiquitinating MEK2 and stabilizing it, which promoted the growth of hepatocellular cancer." (PMID 38906857, 2024). "The UPS also regulates the ERK signaling pathway by affecting MEK1/2 expression, with USP21 involved in maintaining MEK2 stability and activating ERK signaling in hepatocellular carcinoma." (PMID 39048965, 2024). "In a nitrosodiethylamine (NDEA)-induced liver cancer model and hepatocellular carcinoma CL38 cells, USP21 markedly increased and downregulated H2Aub." (PMID 35846989, 2022). "BRCA2 overexpression was able to partially restore colony formation in USP21-depleted hepatoma cells, supporting a role for BRCA2 as a mediator of USP21-dependent tumor growth." (PMID 28743957, 2017). "Importantly, we find that USP21 is the most highly amplified DUB in hepatocellular carcinoma (HCC), a BRCA2-proficient tumor with poorly understood molecular pathways of carcinogenesis, a scarcity of druggable targets and a dismal therapeutic outcome." (PMID 28743957, 2017).
non-small cell lung carcinoma (9 papers, 2020 to 2024). A group of at least three distinct histological types of lung cancer, including non-small cell squamous cell carcinoma, adenocarcinoma, and large cell carcinoma. "USP21 can promote tumorigenesis by increasing the cell proliferation, migration, and invasion of non-small cell carcinoma cells." (PMID 37714937, 2023). "In contrast, ubiquitin specific protease 21 (USP21) stabilizes YY1 in non-small-cell lung cancer cells via mediating its deubiquitination." (PMID 35103856, 2022). "Fangbao Ding, Jianbing Huang, and co-workers at Shanghai Jiao Tong University in Shanghai, China, have shown how an enzyme called USP21 promotes cancer cell proliferation and tumor growth in non-small-cell lung cancer." (PMID 31956270, 2020). "Furthermore, the USP21/YY1/SNHG16/miR-4500 axis has been found to assist in the development of non-small-cell lung cancer (NSCLC)." (PMID 35846989, 2022). "In pancreatic cancer and non-small cell lung cancer (NSCLC), various DUBs have also been found to be highly expressed, including OTUD3, USP5, USP17, USP21, USP26, and USP28, which usually predicts dismal prognostic outcome." (PMID 37251574, 2023).
pancreatic cancer (9 papers, 2019 to 2024). "In recent few years, increasing evidence has verified that USP21 functions as an oncogene in a variety of human cancers, including gastric cancer, pancreatic cancer, liver cancer, renal cell carcinoma, colorectal cancer, breast cancer, and lung cancer." (PMID 38906857, 2024). "Previous research found that the nuclear localization of USP21 in pancreas cancer is positively correlated with advanced tumor grades and expression levels, and overexpression of USP21 promotes cell stemness." (PMID 33791299, 2021). "For instance, USP21 stimulates the stemness of pancreatic cancer cells by activating the Wnt pathway." (PMID 33791299, 2021). "In PDAC and CRC, a study found that resistance to anti-KRAS therapy may be driven by deubiquitinase USP21, which promotes KRAS-independent tumor growth by regulating MARK3-induced macrophagocytosis, and thus, USP21 may serve as a new target for the treatment of pancreatic cancer." (PMID 36675641, 2023). "In addition, USP21 encourages malignant HIF-1-driven metabolic reprogramming and may be a target for pancreatic carcinoma treatment." (PMID 37573347, 2023).
colorectal cancer (7 papers, 2020 to 2026). A primary or metastatic malignant neoplasm that affects the colon or rectum. "In this study, we uncovered for the first time that high USP21 promotes colorectal cancer (CRC) cell proliferation and progression, correlates with adverse patient prognosis, induces immunosuppression in TME, and confers resistance to immunotherapy." (PMID 38834869, 2024). "The emerging role of ubiquitin-specific peptidase 21 (USP21) in stabilizing Fra-1 (FOSL1) highlights its involvement in promoting colorectal cancer (CRC) metastasis." (PMID 39695128, 2024). "The Ubiquitin-Specific Protease 21 (USP21) is a Fra-1 deubiquitinase contributing to Fra-1 accumulation in KRAS-transformed colorectal cancer cells." (PMID 35326630, 2022). "Consistently, clinicopathological analysis of colorectal cancer patients revealed a correlation of USP21 expression with high-grade carcinoma and life span." (PMID 31947604, 2020). "Considering that Fra-1 and its AP-1 transcriptional activity are highly elevated in primary tumors and metastases, the implication of USP21 in colorectal cancers is consistent with its increase in Fra-1 stability via deubiquitination activity." (PMID 31947604, 2020). "Additionally, alterations in USP21 expression showed significant correlations with multiple methylation sites, implying the potential role of methylation in regulating USP21 expression in colorectal cancer and impacting tumor prognosis." (PMID 38834869, 2024). "Moreover, USP21 promotes the migration and invasion of colorectal cancer by acting as a DUB for Fos-related-antigen-1 (Fra-1), a transcription factor essential for cancer progression and metastasis." (PMID 35846989, 2022). "Interestingly, USP21 expression was significantly enriched in colorectal cancers with frequent lymph node metastasis (N2b, number of cancer cell-positive lymph nodes ≥4) and high number of endolymphatic tumor emboli." (PMID 31947604, 2020). "In addition, the present study shows that USP21 knockdown decreases tumor formation and cancer metastasis in vivo using a mouse model, and USP21 expression is upregulated in colorectal cancer patients." (PMID 31947604, 2020). "In addition, USP21 level was significantly increased in stage 4 colorectal cancer compared to earlier stages (Stages 1 and 2)." (PMID 31947604, 2020). "In the context of colorectal cancer (CRC) metastasis, USP21 plays a crucial role by stabilizing Fra-1 through deubiquitination, thereby promoting the expression of metastasis-related genes like MMPs." (PMID 39695128, 2024). "Many studies have validated that USP21 plays an essential role in the occurrence and progression of various cancers including HCC, colorectal cancer, and urothelial cancer." (PMID 35846989, 2022). "Nonetheless, there is currently a lack of research on the prognostic significance of USP21 in colorectal cancer and its regulatory mechanisms within the TME." (PMID 38834869, 2024). "However, the correlations between USP21 and immunosurveillance and immunotherapy for colorectal cancer (CRC) have not been reported." (PMID 38834869, 2024).
renal cell carcinoma (6 papers, 2016 to 2025). "Furthermore, the inhibition of IL-8, a chemokine that regulates the properties of CSCs in renal cell carcinoma, was found to be associated with decreased levels of the deubiquitinating enzyme USP21." (PMID 40034124, 2025). "However, the effects and underlying mechanism of USP21 on renal cell carcinomas (RCC) remain unclear." (PMID 27259257, 2016). "This pro-cancer effect is also seen in USP21-induced expression of IL-8 via epigenetic modulation, which promotes tumorigenic properties in renal cell carcinomas (RCC), including cell proliferation, invasion, and cancer stem cells percentage." (PMID 35846989, 2022). "USP21 is upregulated in renal cell carcinoma tissues and cell lines, and depletion of USP21 inhibits cell proliferation and invasion through binding to the IL-8 promoter region and mediating transcriptional initiation." (PMID 30459344, 2018). "Thus far, a study proved that USP21 can accelerate cell growth, invasion, and stemness of renal cell carcinoma." (PMID 33791299, 2021). "Interestingly, one study reported that USP21 promoted the tumorigenic properties by acting as a transcription factor to initiate the transcription of IL-8 in renal cell carcinoma which indicates the deubiquitinase-independently cancer-promoting mechanism of USP21." (PMID 38906857, 2024).
breast carcinoma (5 papers, 2017 to 2024). "Another study about basal-like breast cancer reported that USP21 promoted the progression of the cell cycle and resistance to paclitaxel by regulating FOXM1 deubiquitination." (PMID 38906857, 2024). "Ubiquitin specific protease 21 (USP21) is a member of USPs with elevated expression in several cancers, including pancreatic, non–small cell lung, renal, and breast cancers." (PMID 39305962, 2024). "FOXM1 deubiquitinated by USP21 modulates cell cycle and paclitaxel sensitivity of basal-like breast cancer cells." (PMID 35799265, 2022). "In addition, knocking down USP21 promoted the growth of A549 (lung cancer cells) and MDA-MD-231 (breast cancer cells) in soft agar which suggests the tumor-suppressing role of USP21." (PMID 38906857, 2024). "In addition, we also found that USP21 inhibition suppressed soft agar growth of metastatic breast cancer MDA-MB-468 cell lines." (PMID 28969054, 2017).
cholangiocarcinoma (5 papers, 2017 to 2025). A carcinoma that arises from the intrahepatic biliary tree (intrahepatic cholangiocarcinoma) or from the junction, or adjacent to the junction, of the right and left hepatic ducts (hilar cholangiocarcinoma). "In cholangiocarcinoma, USP21 enhances the protein stability of HSP90 and ENO1 by removing their K48-linked ubiquitin chains." (PMID 41301681, 2025). "This review synthesizes current knowledge on six USP members—USP1, USP3, USP8, USP9X, USP21, and USP22—and delineates their context-dependent roles across cholangiocarcinoma and GBC subtypes." (PMID 41301681, 2025). "For instance, ENO1 is directly stabilized by ubiquitin-specific protease 21 (USP21), which enhances chemoresistance to GEM in cholangiocarcinoma." (PMID 40264038, 2025). "Targeting the USP21/HSP90/HIF1α and USP21/ENO1 signaling axes may provide a rational basis for precision therapies and improved prognostication in cholangiocarcinoma." (PMID 41301681, 2025). "Furthermore, patients with cholangiocarcinoma had poor prognoses and overall survival regardless of whether USP21 was highly expressed simultaneously with HSP90 or HIF1A." (PMID 38385089, 2024).
gastric cancer (5 papers, 2021 to 2024). A primary or metastatic malignant neoplasm involving the stomach. "In gastric cancer, USP21 increased the expression level of MAPK1 to promote malignant progression by binding and stabilizing the transcription factor GATA3." (PMID 38906857, 2024). "In a comprehensive pan-cancer analysis, USP21 emerged as significantly upregulated across various gastrointestinal malignancies, including colon, esophageal, liver, and stomach cancers." (PMID 38834869, 2024). "GATA3 is a substrate of USP21 involved in immune tolerance, and this interaction was also found in gastric cancer, which further facilitated the malignant progression of gastric cancer by promoting MAPK1 (also known as ERK2) expression." (PMID 35846989, 2022). "USP21 is a kind of deubiquitinating enzymes involved in the malignant progression of various cancers, while its role in gastric cancer (GC) and the specific molecular mechanism are still unclear." (PMID 33791299, 2021). "USP21 deubiquitinates MAPK1 by interacting with GATA3, impacting gastric cancer growth and stem cell properties." (PMID 39605891, 2024).
lung carcinoma (5 papers, 2017 to 2025). "Functional studies using USP21-knockout (USP21-KO) lung cancer cell lines demonstrated reduced proliferation, migration, colony formation, and tumor spheroid growth." (PMID 40629473, 2025). "To expand our claims of the role of USP21 in cancer biology we decided to analyze the effect of USP21 silencing on proliferation, migration, and colony formation in the A549 cell line of non–small cell lung cancer." (PMID 39305962, 2024). "Stable expression of USP21 shRNAs led to increased CTGF and Cyr61 expression in BJ fibroblasts, lung carcinoma A549 cells and in metastatic breast cancer MDA-MB-231 cells." (PMID 28969054, 2017). "STAT3 may be involved in different USP21-mediated cancer progression pathways, such as USP21-YY1-SNHG16 axis in non–small cell lung cancer." (PMID 39305962, 2024).